CD200 (CD200 molecule)
Description:
Costimulates T-cell proliferation. May regulate myeloid cell activity in a variety of tissues.
Synonyms: MOX1; MOX2; MRC; OX-2
Tractability: Antibody: a drug acting on it is in phase 2 or 3 trials; its Gene Ontology location is reachable by antibodies, with high confidence; UniProt places it where antibodies can reach, with medium confidence; UniProt predicts a signal peptide or a membrane-spanning region. PROTAC: its protein half-life has been measured.
Gene: Protein-coding gene on chromosome 3 (112,332,235 to 112,363,181, forward strand). Ensembl gene ENSG00000091972.
Subcellular location: Cell membrane
Pathways (Reactome):
Immune System: Immunoregulatory interactions between a Lymphoid and a non-Lymphoid cell
Gene Ontology:
Molecular function: protein binding; cell-cell adhesion mediator activity; glycosylated region protein binding; protein binding involved in heterotypic cell-cell adhesion
Biological process: cellular response to lipopolysaccharide; cellular response to type II interferon; heterotypic cell-cell adhesion; negative regulation of canonical NF-kappaB signal transduction; negative regulation of matrix metallopeptidase secretion; positive regulation of macrophage activation; positive regulation of transcription by RNA polymerase II; positive regulation of transforming growth factor beta production; cell-cell adhesion; negative regulation of cell population proliferation; negative regulation of interleukin-6 production; negative regulation of leukocyte activation; negative regulation of macrophage activation; negative regulation of macrophage migration; negative regulation of neuroinflammatory response; negative regulation of T cell migration; regulation of neuroinflammatory response; regulation of immune response; regulation of macrophage activation
Cellular component: axon; cell body; cell surface; neuronal cell body; membrane; neuron projection; plasma membrane
Genetic constraint (gnomAD): Loss-of-function variants: 12 observed, 22.87 expected, observed/expected ratio (o/e) 0.52, 90% interval 0.34 to 0.85. The upper end of that interval is the gene's LOEUF score, 0.85, which puts it in group 3 of 6, group 1 being the genes least tolerant of losing a copy. Missense variants: 228 observed, 300.58 expected, observed/expected ratio (o/e) 0.76, 90% interval 0.68 to 0.85. Synonymous variants: 120 observed, 117.33 expected, observed/expected ratio (o/e) 1.02, 90% interval 0.88 to 1.19.
Homologues: Orthologues: chimpanzee CD200 (99% identical), macaque CD200 (95% identical), rabbit CD200 (78% identical), mouse Cd200 (77% identical), rat Cd200 (76% identical), dog CD200 (72% identical), guinea pig CD200 (68% identical), pig CD200 (67% identical), zebrafish si:dkey-31e10.1 (21% identical), zebrafish si:dkey-31e10.5 (21% identical), Drosophila melanogaster Fas3 (17% identical). Paralogues in human: NECTIN1 (23% identical), NECTIN3 (23% identical), NECTIN2 (22% identical), PVR (20% identical), NECTIN4 (19% identical), CADM2 (18% identical), CADM3 (16% identical), CRTAM (16% identical), CD226 (16% identical), CADM1 (15% identical), CADM4 (14% identical), TIGIT (12% identical), and 2 more.
Diseases named in the same sentence as CD200 in open-access papers:
CD200 is named in the same sentence as 215 diseases in open-access papers, as found by Europe PMC text mining. Sharing a sentence is not in itself a finding about the gene and the disease. The quoted sentences say what the papers report.
breast carcinoma (33 papers, 2014 to 2025). "The overexpression of CD200 in breast cancer cells is associated with accelerated tumor growth and impairs prognoses." (PMID 39795972, 2024). "The overexpression of CD200 in breast cancer is associated with increased tumorgenicity, metastasis and poor prognosis." (PMID 39795972, 2024). "In some tumors, such as central nervous system tumors and breast cancer, CD200 overexpression has been associated with a pro-tumorigenic effect." (PMID 38619621, 2024). "In breast cancer, a high expression of CD200 is associated with enhanced tumor growth, although the effects on metastasis are inconsistent." (PMID 39795972, 2024). "The overexpression of CD200 in breast cancer can be considered as an important risk factor of metastasis." (PMID 34236536, 2021). "So far, Several reports concluded that CD200 expression is also associated with the progression of various solid cancers, such as bladder cancer, lung cancer, breast cancer prostate carcinoma, cutaneous squamous cell carcinoma and acute myeloid leukemia." (PMID 32856848, 2020). "Serum levels of soluble CD200 proteins have the potential to become a diagnostic tool for breast cancer, and the level of CD200R may offer some idea of the stages of the disease, but these studies still require additional confirmation and validation." (PMID 39795972, 2024). "CD200 levels may, thus, be one additional factor in defining metastatic risk, perhaps differently for the various subtypes of breast cancer." (PMID 39795972, 2024). "Specifically, CD200 has been associated with pathologic and prognostic outcomes in breast cancers." (PMID 39795972, 2024). "In a 4THM breast carcinoma murine model, CD200 overexpression in CD200 transgenic BALB/c mice was correlated with the complete regression of primary tumors." (PMID 40718780, 2025). "Future studies should examine the influence of the microbiome on CD200 expression by both tumor and immune cells during human breast cancer." (PMID 39795972, 2024). "CD200 is a recently identified cell surface glycoprotein recognized as an important molecule in breast cancer for its versatile modulation of the immune response via its receptor, CD200R." (PMID 39795972, 2024). "A high heterogeneity has also been found in the expression of CD200 between different types of breast cancer." (PMID 39795972, 2024). "Effective targeted therapies for CD200 thus appear to be challenging because CD200 expression varies widely across different tumor types, including breast cancers." (PMID 39795972, 2024). "Among the important effects of CD200 expression by breast cancer cells are those on the interactions with immune cells in the microenvironment." (PMID 39795972, 2024). "These advances should lead to more effective and precise strategies and make CD200-targeted treatments a standard part of the treatment options for advanced breast cancer." (PMID 39795972, 2024). "In this review, we will discuss the immune actions, functional modes, and therapeutic developments of CD200 in the context of breast cancer, with a special emphasis on recent advances in molecular biology, clinical research and therapeutic innovations." (PMID 39795972, 2024). "The controversial involvement of CD200 in tumor metastasis, its differential expression, and its heterogeneous impact on tumor growth indeed complicate its targeting in breast cancer." (PMID 39795972, 2024). "Treatments targeting CD200 thus provide a promising opportunity to improve outcomes in the management of breast cancer, although additional confirmation in clinical trials is needed." (PMID 39795972, 2024). "This represents the potential of CD200 as a therapeutic target in the treatment of breast cancer and other cancers." (PMID 39795972, 2024). "CD200 is an inhibitory molecule that dampens the antitumor immune function, a potential target for immune checkpoint therapy in breast cancer." (PMID 39795972, 2024).
breast carcinoma (continued). "The ongoing anti-CD200 trials are mainly focused on proving the efficacy and safety of these treatments in patients with breast cancers." (PMID 39795972, 2024). "It indicates that the doxorubicin induces the dysregulation of hiPSC-CMs derived RAD9A, HSPA1B, GATA2, IGF2R, CD200, ERCC8, and BCL11A genes that are associated with the pathogenesis of doxorubicin-induced cardiotoxicity in breast cancer patients." (PMID 37684436, 2023). "Expression of CD200 was also significantly upregulated in bone, lung, and liver metastatic lesions of breast cancer." (PMID 33932112, 2021). "Coincidentally, cell surface proteome profiling revealed CD200 as one of the markers specifically upregulated on metastatic breast cancer primary explants." (PMID 33932112, 2021). "CD200 molecule (CD200) serum levels are significantly higher in the early and the advanced stage breast cancer patients." (PMID 30918839, 2019). "Among which, IBSP, MMP9, TNFAIP6, DHRS3, RIPK4, and CD200 had a diagnose value for patients with breast cancer bone metastasis." (PMID 30918839, 2019). "We previously observed that visceral metastasis of highly aggressive and inflammatory 4THM breast carcinoma cells was markedly decreased in CD200 transgenic mice." (PMID 29721190, 2018). "We previously documented that CD200 has a bidirectional effect on tumor growth and metastasis of breast carcinoma which depends on immunological response created by the tumor." (PMID 29721190, 2018). "Here, we examined the effects of CD200 on tumor growth, metastasis, and anti-tumour immune responses to orthotopically-injected 4THM breast carcinoma cells using BALB/c female mice." (PMID 29721190, 2018). "Specifically over expression of CD200 in the host reduced the progression and metastasis of highly aggressive and inflammatory 4THM murine breast carcinoma." (PMID 29721190, 2018). "We have compared cure from local/metastatic tumor growth in BALB/c mice receiving EMT6 or the poorly immunogenic, highly metastatic 4THM, breast cancer cells following manipulation of immunosuppressive CD200:CD200R interactions or conventional chemotherapy." (PMID 25409195, 2014). "While the overexpression of anti-cell death proteins, such as BAG3, and other pathways protective against cell damage confer cancer resistance, their contribution to the outcome of CD200-targeted therapies against breast cancer remains unclear." (PMID 39795972, 2024). "Advanced computer modeling to predict patient outcomes with CD200-targeted therapies could significantly enhance personalized treatment in breast cancer." (PMID 39795972, 2024). "Studies confirmed the roles of CD200 in immune escape during the course of breast cancer." (PMID 39795972, 2024). "CD200 therapy in breast cancer could only be developed through clinical trials, which need to consider not only efficacy, but also safety and integration." (PMID 39795972, 2024). "This suggests that CD200 could be important in metastasis and immune escape in breast cancer, although further validation is needed." (PMID 39795972, 2024). "The capability of CD200 was further recorded in other malignancies, such as melanoma, renal cell carcinoma and ovarian tumors, using anti-CD200 antibodies, which were shown to initiate vigorous immune responses against breast cancer and other solid tumor types." (PMID 39795972, 2024). "Breast cancer cells take advantage of the complicated molecular interactions within their microenvironment to evade the immune system and acquire resistance against CD200 therapies." (PMID 39795972, 2024). "Targeting immune checkpoint CD200 in breast cancer is challenging but shows great promise." (PMID 39795972, 2024). "Further, the role of CD200 in metastasis in breast cancers was demonstrated in studies showing that the neutralization of CD200 by monoclonal anti-CD200 antibodies decreases tumor metastases and was associated with increased cytotoxic antitumor immune cell flux into the regional lymph nodes." (PMID 39795972, 2024).
breast carcinoma (continued). "High CD200 levels in breast cancer cells may also impact immune cells in lymph nodes and be related to lymph node status." (PMID 39795972, 2024). "For example, the expression of CD200 expression may vary, such as in basal-like breast cancers, which lack estrogen receptors and HER2 but express basal cytokeratin, HER1, or cKIT." (PMID 39795972, 2024). "Targeting therapy through the use of CD200 represents one of the new approaches to manage breast cancer and may contradict the immune escape mechanisms developed by cancer cells." (PMID 39795972, 2024). "In fact, the biomarkers for IRAE are critical, and for these therapies targeting CD200 to be safe and effective in breast cancers, more clinical data accumulation will require further clarification on how those risks could be reduced." (PMID 39795972, 2024). "However, there are several similarities in the behavior of CD200 in breast cancer and other cancers, even though it seems to act somewhat differently." (PMID 39795972, 2024). "Thus, it indicates the role of CD200 in a dual manner for the progression and metastasis of breast cancers." (PMID 39795972, 2024). "The safety and effectiveness of vaccines targeting CD200 in breast cancer were also tested." (PMID 39795972, 2024). "On the other hand, CD200 neutralization provoked a profound humoral immune response against tumors expressing this molecule, including mammary tumors, and its combination with other therapies could offer a more robust antitumor activity." (PMID 39795972, 2024). "Whereas CD200 knockdown by shRNA significantly reduced lung metastasis and CD200-/- mice exhibited increased resistance to chemically induced papillomas, reduced metastasis burden in the 4THM breast cancer model in mice overexpressing CD200 has also been reported." (PMID 37082107, 2023). "In a murine breast cancer model, it was reported that growth of tumor in an immunocompetent environment “selected” for growth of CD200+ tumor cells, while expression of mCD200 on breast cancer cells (BTAK+) was decreased following growth in immunosuppressed mice." (PMID 33562512, 2021). "Synergistic inhibition of stemness‐related pathways including Wnt, TGF‐β, and Hedgehog signaling may improve the efficacy of ICB treatment targeting CD200 or CD276 in breast cancer stem cells." (PMID 33932112, 2021). "Moreover, CD200fc, which mimics the effect of CD200, significantly decreased tumor growth and metastasis in a mouse model of breast cancer, increased IFN-γ and decreased IL-6 expression, and time-dependently altered IL-10 and IL-17 levels." (PMID 32635224, 2020). "The research of TNFAIP6, DHRS3, ASS1, RIPK4, VIM, and CD200 in breast cancer may indicate that those genes may play a crucial role in the development of breast cancer bone metastasis." (PMID 30918839, 2019). "It is reported that CD200 analogs may have therapeutic potential in treating aggressive breast carcinoma." (PMID 30918839, 2019). "The transplantable EMT6 mouse breast cancer line expresses low levels of CD200 in vitro, but upregulates CD200 following inoculation into immunocompetent mice; this is similar to PD-L1, which is often expressed at low levels in vitro, but rapidly upregulated in immune active environments." (PMID 28515726, 2017). "Again we wondered whether this reflected a greater importance to tumor (vs host) CD200 expression in regulation of breast cancer growth in vivo." (PMID 28234914, 2017). "In summary, our data support the hypothesis that CD200 blockade may be an effective therapeutic target in breast cancer." (PMID 28234914, 2017). "Recent data from our laboratory suggests that sCD200 can also be detected in the serum of breast cancer and colonic cancer patients (unpublished data), consistent with the growing evidence that CD200 itself is reported to be overexpressed in a number of human cancers." (PMID 27111430, 2016).
breast carcinoma (continued). "A series of studies demonstrated that overexpression of CD200 promotes tumor growth and metastasis of breast cancer in immunocompetent mice through suppression of the immune response, a process that can be reversed by treatment with an anti-CD200 monoclonal antibody." (PMID 24944582, 2014). "Moreover, the role of CD200 in immune evasion and treatment resistance in pancreatic cancer hints at its potential effects as a biomarker for analogous therapeutic strategies in breast cancer, covering pre- and post-surgery interventions." (PMID 39795972, 2024). "Thus, the CD200-targeting therapies may better be combined with other treatment modes to attain the maximal benefits for breast cancer patients." (PMID 39795972, 2024). "As the high expression of CD200 in cutaneous squamous cell carcinoma is related to immune evasion, it is considered a potential biomarker predictive of reduced overall survival and may imply similar roles in breast cancer." (PMID 39795972, 2024). "Preliminary studies highlighted that CD200-targeted therapies have potential as immunomodulatory drugs that show promise, especially in CNS-related cancers; this principle may even be applicable to breast cancer." (PMID 39795972, 2024). "Thus, CD200-targeted therapies may greatly enhance the treatment of breast cancers by offering a multi-target approach that may alter the course of current treatments." (PMID 39795972, 2024). "Conversely, CD200 has also been shown to exert anti-tumor effects in certain cancer types, such as breast carcinoma and melanoma, indicating that CD200 may exert bidirectional effects on cancer progression depending on the specific tumor microenvironment (TME)." (PMID 38137547, 2023). "In this study, the strong association of TGF‐β signaling with the cancer stem cell–specific immune checkpoints implies that inhibition of TGF‐β signaling may impede CD200‐ or CD276‐mediated immune evasion of breast cancer stem cells, which has rarely been described before." (PMID 33932112, 2021). "That suggested the infiltration of CD8+ T cells, dendritic cells, or M1 macrophages in breast cancer can signify prolonged patient survival, and that the expression of CD200 and CD276 in cancer stem cells could impair the tumoricidal function of CD8+ T cells, dendritic cells, and M1 macrophages." (PMID 33932112, 2021). "Our data suggest that optimal treatment of breast cancer should take into consideration the importance in "trade-off" between cancer cell sterilization by immunosuppressive drug treatment and the potential benefit of enhancing immune resistance by manipulation of co-inhibitory (CD200) pathways." (PMID 25409195, 2014). "The ectodomain of CD200 has been reported to be shed, and the resulting sCD200 has been reported in the plasma of patients with various types of cancers, including CLL and breast cancer." (PMID 38619621, 2024). "Currently, antibodies targeting CD200 and CD200R are being developed for the purpose of the immunotherapy treatment of breast cancers." (PMID 39795972, 2024). "With the combination of CD200-targeted therapies and the endocrine treatment of hormone receptor-positive, the treatment of HER2-negative breast cancers is expected to be promising." (PMID 39795972, 2024). "Previously, we reported CD200 and CD276, respectively, as candidate innate and adaptive immune checkpoints in breast cancer stem cells." (PMID 36494785, 2022). "Following the principle, our study revealed CD200 and CD276 as candidate immune checkpoints in breast cancer stem cells." (PMID 33932112, 2021). "CD200 and CD276 are candidate inhibitory immune checkpoints in breast cancer stem cells, which are potentially regulated by Wnt, TGF‐β, and Hedgehog signaling." (PMID 33932112, 2021). "Of note, levels of CD200 and CD276 expression were higher in TGF‐β dominant breast cancer than in other immune types of breast cancer." (PMID 33932112, 2021).